SEC14L5 (SEC14 like lipid binding 5)
Synonyms: KIAA0420; PRELID4B
Tractability: PROTAC: ubiquitination databases record sites on it.
Gene: Protein-coding gene on chromosome 16 (4,958,295 to 5,019,157, forward strand). Ensembl gene ENSG00000103184.
Subcellular location (Human Protein Atlas): Cytosol; Golgi apparatus
Gene Ontology:
Molecular function: protein binding
Cellular component: cytoplasm
Genetic constraint (gnomAD): Loss-of-function variants: 95 observed, 75.68 expected, observed/expected ratio (o/e) 1.26, 90% interval 1.06 to 1.49. The synonymous counts are far from expectation, so gnomAD's model fits this gene poorly and the ratio says little. Missense variants: 1,209 observed, 890.51 expected, observed/expected ratio (o/e) 1.36, 90% interval 1.29 to 1.42. Synonymous variants: 541 observed, 364.6 expected, observed/expected ratio (o/e) 1.48, 90% interval 1.38 to 1.59.
Homologues: Orthologues: chimpanzee SEC14L5 (99% identical), macaque SEC14L5 (98% identical), dog SEC14L5 (89% identical), mouse Sec14l5 (88% identical), rat Sec14l5 (88% identical), guinea pig SEC14L5 (88% identical), pig SEC14L5 (87% identical), rabbit SEC14L5 (76% identical), tropical clawed frog sec14l1 (74% identical), Caenorhabditis elegans T23G5.2 (47% identical), Drosophila melanogaster retm (45% identical), Caenorhabditis elegans F28H7.8 (15% identical), and 3 more. Paralogues in human: SEC14L1 (69% identical), SEC14L4 (19% identical), SEC14L2 (19% identical), SEC14L3 (19% identical), SEC14L6 (18% identical), TTPA (10% identical).
Diseases named in the same sentence as SEC14L5 in open-access papers:
SEC14L5 is named in the same sentence as 15 diseases in open-access papers, as found by Europe PMC text mining. Sharing a sentence is not in itself a finding about the gene and the disease. The quoted sentences say what the papers report.
cardiomyopathy (1 paper, 2017). A disease of the heart muscle or myocardium proper. "Only one gene was inversely regulated in RCM compared to the Common Cardiomyopathy dataset: SEC14-like 5 (SEC14L5), an integral membrane protein with predicted transporter activity." (PMID 28098235, 2017).
lung carcinoma (1 paper, 2015). "We selected seven genes (CRP, GPC5, ACTA2, AGPHD1, SEC14L5, RBMS3, and GKN1) that previously reported link to lung cancer (LC) and genotyped single nucleotide polymorphisms (SNPs) of these genes in a case-control study." (PMID 25999661, 2015).
SEC14L5 also shares sentences with these, for which no sentence is quoted: cancer (2 papers); breast carcinoma (1); colon cancer (1); gastric cancer (1); head and neck squamous cell carcinoma (1); hyperprolinemia type 2 (1); mastitis (1); melanoma (1); myeloproliferative neoplasm (1); non-small cell lung carcinoma (1); ovarian carcinoma (1); pancreatic cancer (1); renal cell carcinoma (1).